KIF18B (kinesin family member 18B)
Diseases named in the same sentence as KIF18B in open-access papers (continued):
Sharing a sentence is not in itself a finding about the gene and the disease.
glioma (2 papers, 2015 to 2025). A benign or malignant brain and spinal cord tumor that arises from glial cells (astrocytes, oligodendrocytes, ependymal cells). "Subsequent analysis of the clinical implications of these genetic modifications in gliomas revealed a partial correlation between KIF18B expression and its methylation status in mutated instances." (PMID 40110038, 2025). "Multivariable COX regression analysis and ROC curve showed that KIF18B was one of the independent risk factors for glioma prognosis." (PMID 40110038, 2025). "This investigation marks the first utilization of the cBioPortal database to analyze the genetic alterations of KIF18B in glioma, with mutation being the predominant type." (PMID 40110038, 2025). "To investigate whether high expression of KIF18B is associated with poor prognosis in glioma patients, we obtained prognostic follow-up data from the TCGA dataset." (PMID 40110038, 2025). "Therefore, we speculate that high expression of KIF18B may also be associated with poor prognosis in glioma patients." (PMID 40110038, 2025). "The bioinformatics outcomes of the present study suggest that the hypomethylation of the KIF18B gene may be implicated in the upregulated expression of KIF18B in gliomas, and individuals with hypomethylated KIF18B gene status experience a less favorable prognosis." (PMID 40110038, 2025). "The results indicated that KIF18B primarily regulates the malignant progression of glioma through cellular functions related to mitosis, cell cycle regulation, and the Rb-E2F signaling pathway." (PMID 40110038, 2025). "Based on these findings, it is justified to conclude that KIF18B influences the malignant progression of glioma via these cancer-relevant signaling pathways." (PMID 40110038, 2025). "To elucidate the role of KIF18B in glioma, we divided glioma samples into high and low expression groups based on the median expression value of KIF18B in the TCGA dataset." (PMID 40110038, 2025). "The results revealed that KIF18B expression in gliomas was significantly increased, with higher expression in GBM compared to LGG (p < 0.05)." (PMID 40110038, 2025). "The results indicated that in glioma patients, overall survival, progression-free interval, and disease-specific survival were significantly lower in patients with high KIF18B expression compared to those with low expression." (PMID 40110038, 2025). "We then performed GSEA to identify significantly activated pathways in glioma patients with high KIF18B expression compared to those with low expression." (PMID 40110038, 2025). "Beyond that, the expression of immune checkpoint molecules in glioma patients with high expression of KIF18B was higher than that in glioma patients with low expression of KIF18B." (PMID 40110038, 2025). "Additionally, the CGGA and TCGA datasets showed that higher expression of KIF18B correlated with higher glioma grade (p < 0.05)." (PMID 40110038, 2025). "Therefore, the objective of this study was to elucidate the relationship between KIF18B expression and the clinical and molecular characteristics of glioma." (PMID 40110038, 2025). "To delineate the biological role of KIF18B in glioma, we performed GO, KEGG analysis, and GSEA." (PMID 40110038, 2025). "Kaplan-Meier survival analysis, ROC curves for 1, 3, and 5-year survival intervals, and multivariate Cox regression analysis all consistently indicated that KIF18B may function as an independent predictor of unfavorable prognosis in glioma patients." (PMID 40110038, 2025). "To more directly analyze the expression level of KIF18B in gliomas, we accessed the GEPIA database." (PMID 40110038, 2025).
glioma (continued). "Our results demonstrate for the first time the key role of KIF18B in the process of glioma canceration, thus proving that it is highly likely to be used as a potential therapeutic target for the treatment of glioma, igniting new hopes for improving the survival and prognosis of patients with glioma." (PMID 40110038, 2025). "KIF18B was highly expressed in various cancers including GBM, and was positively correlated with glioma grade and negatively correlated with prognosis." (PMID 40110038, 2025). "Hence, the present study was designed to examine the expression of KIF18B in GBM and its clinical implications using mRNA expression data from the TCGA and CGGA databases, with the goal of identifying novel therapeutic targets and advancing glioma research." (PMID 40110038, 2025).
liver cancer (2 papers, 2020 to 2023). An epithelial or non-epithelial malignant neoplasm that arises from the liver. "Likewise, prior research showed that KIF18B facilitated the progression of breast and liver cancers via EMT activation." (PMID 37744335, 2023).
nasopharyngeal carcinoma (2 papers, 2023 to 2024). A carcinoma arising from the nasopharyngeal epithelium. "It has been revealed that the overexpression of KIF18B, a microtubule motor protein that facilitates chromosomal separation and positioning during the process of cell division, in nasopharyngeal carcinoma may be a predictive biomarker for therapeutic response in chemotherapy and immunotherapy." (PMID 39201656, 2024).
head and neck squamous cell carcinoma (1 paper, 2023). A squamous cell carcinoma that arises from any of the following anatomic sites: lip and oral cavity, nasal cavity, paranasal sinuses, pharynx, larynx, and salivary glands. "KIF18B has been implicated in the immune infiltration of various tumors, including head and neck squamous cell carcinoma (HNSCC)." (PMID 37744335, 2023).
lymph node metastasis (1 paper, 2026). "We found that KIF18B expression is significantly upregulated in OS tissues and correlates with lymph node metastasis (N-stage) and clinical stage." (PMID 41977416, 2026).
metastatic melanoma (1 paper, 2023). A melanoma that has spread from its primary site to another anatomic site. "Among the top 5 candidate genes (UBE2C, ASF1B, FOXM1, HJURP, and KIF18B), UBE2C was the most frequently associated with poor prognosis in publicly available clinical datasets from diverse cancer types, including metastatic melanoma." (PMID 37215954, 2023).
ovarian carcinoma (1 paper, 2022). A malignant neoplasm originating from the surface ovarian epithelium. "Eight genes (NUF2, GTSE1, DEPDC1, KIF18B, PBK, CEP55, HJURP, SKA1) were potential hub genes correlated to ovarian cancer progression." (PMID 35173547, 2022).
pancreatic ductal adenocarcinoma (1 paper, 2021). An infiltrating adenocarcinoma that arises from the epithelial cells of the pancreas. "In pancreatic ductal adenocarcinoma, CDCA8 mediates the upregulation of KIF18B and promotes tumour cell proliferation." (PMID 34741389, 2021).
tumor (38 papers, 2015 to 2026). "As reported, KIF18B is a molecular motor protein that destabilizes astral microtubules during mitosis, which promotes tumor development in various cancers and is associated with poor prognosis." (PMID 37234166, 2023). "shown that KIF18B expression was associated closely with tumor immunity and interacted with various immune cells and genes markers." (PMID 35359374, 2022). "The most promising peptides with mutations in Kif18b and Cpsf3l genes were tested separately in vivo for their anti-tumor effect." (PMID 31156619, 2019). "The mutated Kif18b (K739 N) was the dominant mutated antigen, and mice immunized with mutated Kif18b peptide showed decreased tumor progression and improved survival." (PMID 30662919, 2018). "KIF18B-mediated tumor promotion was associated with aberrant WNT/β-catenin signaling." (PMID 38433242, 2024). "In this study, increased KIF18B expression was associated with higher tumor cell purity, which may possibly clarify the positive correlation seen between KIF18B expression and NK cell infiltration." (PMID 37744335, 2023). "Moreover, we were able to unveil the potential mechanisms underlying KIF18B-mediated interactions between tumor cells and adjacent cellular components." (PMID 37744335, 2023). "In this study, we conducted a comprehensive analysis of KIF18B at the transcription level, tumor mutation burden (TMB) level, DNA methylation level, microsatellite instability (MSI) level, mismatch repairs (MMRs) level, TME level, clinical prognosis level, and more." (PMID 34109209, 2021). "In particular, the mutated form of Kif18b (K739 N) was found to be a dominant mutated antigen, and mice immunized with mutated Kif18b peptide could slow tumor growth and improve survival." (PMID 31291991, 2019). "For example, Kif18A is mis-expressed in numerous cancers, which correlates with advanced tumor grade and poor survival, whereas Kif18B has been implicated in tumor progression through Wnt signaling and may be a driver in carcinogenesis." (PMID 30577528, 2018). "Also, TMB, MSI, MMRs, and DNA methylation might contribute to KIF18B dysregulation in cancers, and KIF18B is closely linked to tumor immunity and may be a potential therapeutic target for immunotherapy." (PMID 34109209, 2021). "In the current investigation, a comparative analysis of tumor and normal tissue data across several databases revealed a significant correlation between the upregulation of KIF18B and diverse cancers, including GBM." (PMID 40110038, 2025). "Initially, the cBioPortal database was employed to ascertain KIF18B genetic alterations across various tumor samples within the TCGA dataset." (PMID 40110038, 2025). "To further elucidate the tumor immune function of KIF18B, we used the TIMER2.0 database to analyze the correlation between KIF18B mRNA expression and GBM immune cell infiltration levels." (PMID 40110038, 2025). "The results of immunoassay showed that the expression of KIF18B was correlated with immune infiltration of tumor microenvironment." (PMID 40110038, 2025). "GSEA revealed that the upregulation of KIF18B can enhance the activation of the cell cycle and Rb-E2F signaling pathway, which is consistent with the tumor-related regulatory mechanisms documented in the literature." (PMID 40110038, 2025). "Elucidating the direct downstream targets and mechanisms of KIF18B is essential for a comprehensive understanding of tumor progression dynamics." (PMID 40110038, 2025). "For example, in renal clear cell carcinoma, KIF18B is markedly overexpressed and correlates with a less favorable prognosis and advanced tumor stage." (PMID 40110038, 2025). "We also used the ESTIMATE algorithm score to predict tumor purity, and the results showed that KIF18B expression was negatively correlated with stromal score, immune score, and ESTIMATE score." (PMID 40110038, 2025).
tumor (continued). "Six of them (KIF4A, ASPM, KIF20A, KIF14, TPX2, KIF18B) are overexpressed by more than 10-fold in tumor samples and four of them (KIF11, AURKB, TPX2 and KIFC1) are essential for cell survival." (PMID 37835564, 2023). "Functional enrichment analysis showed that KIF18B plays a vital role in immune regulation; therefore, we further explored the potential functions of KIF18B in the tumor immune microenvironment." (PMID 37744335, 2023). "Six of them (KIF4A, ASPM, KIF20A, KIF14, TPX2, KIF18B) warrant particular attention as they show increased expression by more than 10-fold in tumor samples compared to normal tissues." (PMID 37835564, 2023). "KIF18B is highly expressed in human PAAD tissues and is associated with poor prognosis and clinical characteristics of PAAD patients, such as tumor size and TNM stage." (PMID 36714025, 2023). "A previous study has clarified that KIF-18B was involved in the growth and progression of tumor cells by up-regulating transcription of CDCA8." (PMID 36358852, 2022). "KIF18B is also illustrated to be the oncogenesis to promote tumor progression and enhance therapeutic resistance." (PMID 35873497, 2022). "Repeated vaccination of mRNA encoding a lysine to asparagine (K739N) mutation in the Kif18b slowed tumor growth, prolonged survival, and inhibited lung metastasis in B16F10 tumor model." (PMID 36311701, 2022). "KIF18B correlated closely with tumor immunity and interacted with different immune cells and genes in different cancer types." (PMID 34109209, 2021). "They found that the mice immunized with mutant KIF18B peptide had weaker tumor progression and higher survival rates, which provided an experimental basis for our research results." (PMID 34109209, 2021). "Analysis of the TCGA dataset indicated that KIF18B mRNA levels are significantly elevated in PCa tissues compared with non-tumor adjacent tissues." (PMID 33753726, 2021). "The invasion capacities of the tumor cells were weakened after the knockdown of KIF18B by siRNAs in vitro." (PMID 32973873, 2020). "IHC staining revealed attenuated expression of Ki67, PTEN, KIF18B, and β-catenin in the sh-KIF18B group, indicating that silencing of KIF18B inhibits tumor growth in vivo." (PMID 32587775, 2020). "Emerging research has increasingly highlighted the association between KIF18B and various cancers, with accumulating evidence suggesting that KIF18B is overexpressed in multiple malignancies affecting the respiratory, urinary, and digestive systems, and that it facilitates tumor proliferation." (PMID 40110038, 2025). "In addition, to further confirm the expression of KIF18B in different cancers, we analyzed its expression in tumor tissues using the UCSC online platform." (PMID 40110038, 2025). "Additionally, the ESTIMATE immune algorithm confirmed that higher expression levels of KIF18B correspond to lower immune, tumor-infiltrating lymphocyte, and ESTIMATE scores." (PMID 40110038, 2025). "Consequently, it is imperative to ascertain the impact of KIF18B on the GBM tumor immune microenvironment." (PMID 40110038, 2025). "This suggests that KIF18B may suppress tumor immune responses by facilitating the infiltration of immune cells." (PMID 40110038, 2025). "Conversely, the upregulated gene subset (e.g., SIM2, HJURP, IQGAP3, KIF18B) showed predominantly negative correlations with many IRGs, potentially reflecting an association with the suppression of anti-tumor immune responses." (PMID 41439026, 2025). "On the other hand, the promotive effects mediated by KIF18B in tumor migration and proliferation might be exerted via the WNT/β-catenin signaling axis, given the corresponding changes of downstream pathway proteins following KIF18B interference." (PMID 38433242, 2024). "Our research suggests that the combination of mTOR inhibitors and KIF18B inhibitors may synergistically enhance their preventing recurrence and anti-tumor effect." (PMID 37957153, 2023).
tumor (continued). "In summary, the stimulatory interaction and immune checkpoint modulation between malignant cells and CD4+ Tregs may account for activated Tregs infiltration in the high KIF18B expression group, promoting tumor growth and progression." (PMID 37744335, 2023). "In addition, we examined the expression of tumor immunity-related genes and found that most were negatively correlated with KIF18B expression." (PMID 37744335, 2023). "KIF18B, PD-L1, and Lag-3 showed the same expression trends in tumors, suggesting that they may share some pathways that promote tumor aggressiveness." (PMID 34109209, 2021). "In the present study, we provide the first evidence that KIF18B is overexpressed in PCa compared with non-tumor tissues, as initially determined by bioinformatics analysis of a TCGA dataset and then validated by IHC, IF, RT-qPCR, and Western blot analyses of fresh PCa and paracancerous tissues." (PMID 33753726, 2021). "The effects of KIF18B on PCa tumor growth in vivo were examined in a mouse xenograft model." (PMID 33753726, 2021). "In summary, high KIF18B expression may indicate tumor progression and poor immunotherapy outcomes." (PMID 37744335, 2023). "However, its role in HNSCC differed from that revealed by our findings, implying that KIF18B may exert different effects on tumor-related immunity in NPC and HNSCC." (PMID 37744335, 2023). "The expression difference, survival, pathological stage, DNA methylation, tumor mutation burden (TMB), microsatellite instability (MSI), mismatch repairs (MMRs), tumor microenvironment (TME), immune cell infiltration, and gene co-expression of KIF18B were analyzed using the R language software." (PMID 34109209, 2021). "Additionally, KIF18B was generally higher in the tumor cell lines of 21 tissues." (PMID 34109209, 2021). "Functional experiments demonstrated that KIF18B knockdown markedly suppressed LUAD cell proliferation, migration, and invasion in vitro and inhibited tumor growth in vivo." (PMID 41751942, 2026). "Online analysis of KIF18B transcription levels in tumor and normal tissues using the TIMER database showed that KIF18B was highly expressed in a variety of fatal cancers, including GBM (P < 0.05)." (PMID 40110038, 2025). "KIF18B has been identified as a differentially expressed, upregulated gene in both LUAD and LUSC tumours in the TCGA database based on transcriptomic analyses." (PMID 40002279, 2025). "These candidates included five upregulated genes—NUF2, KIF4A, KIF18B, NEK2, and DLGAP5—and one downregulated gene—LRRK2—in the tumor tissues of TCGA databases." (PMID 36499051, 2022). "Consistently, NUF2, KIF4A, KIF18B, DLGAP5, and NEK2 were highly overexpressed, whereas LRRK2 was significantly downregulated in the tumor tissues of all datasets." (PMID 36499051, 2022). "We also found that KIF18B overexpression activates the PI3K–AKT–mTOR signaling pathway in PCa cells in vitro and in tumor xenografts." (PMID 33753726, 2021). "Nude mice (n = 10/group) were injected subcutaneously with KIF18B-overexpressing or control cells (KIF18B-DU145 and Vector-DU145, respectively), and tumor growth was monitored for 42 days." (PMID 33753726, 2021). "All 6 KIFs selected by LASSO regression were seen overexpressed in tumor samples comparing to normal samples (KIF10, KIF15, KIF18B, KIF4A: P < 0.0001; KIF18A: P = 0.0003; KIF20A: P = 0.0022), which in accordance with bioinformatics results." (PMID 32322170, 2020). "From TCGA tumor expression data via GEPIA2, the top 100 genes positively correlated with LRFN4 expression were determined, among which TPX2 (R = 0.36), KIF18B (R = 0.39), RCE1 (R = 0.53), PCNXL3 (R = 0.49), and SAMD1 (R = 0.48) showed significant correlations (P < 0.001)." (PMID 40386777, 2025).
tumor (continued). "Through an integrative approach that combines classic experimental methodologies with sophisticated bioinformatics analyses, we have ascertained that KIF18B is upregulated in GBM and its expression level increases concomitantly with the advancement of tumor grade." (PMID 40110038, 2025). "Besides, the anti-tumor immunity conferred by CD8+ T cell contributed to tumor regression and improved prognosis in NPC patients, which in line with our finding that low KIF18B expression group exhibited better prognosis." (PMID 37744335, 2023). "Based on this inference, we screened three key miRNAs (hsa-miR-10b-3p, hsa-miR-23b-3p, and hsa-miR-139-3p) targeting four hub mRNAs (CCNB2, KIF18B, PLK1, and TOP2A) using the correlation analysis, survival analysis, expression analyses in stage, distant metastasis, tumor, and normal tissues." (PMID 33869028, 2021). "Histopathological analysis showed noticeable variations in the levels of KIF18B expression among NPC patients with different morphological subtypes and intra-tumoral tumor-infiltrating lymphocytes (TILs) scores, but not in stromal TILs scores." (PMID 37744335, 2023).